CTLA4 (cytotoxic T-lymphocyte associated protein 4)
Diseases named in the same sentence as CTLA4 in open-access papers (continued):
Sharing a sentence is not in itself a finding about the gene and the disease.
melanoma (continued). "In the anti-CTLA-4 cohort, higher SGPP2 expression in melanoma patients was associated with a better therapeutic benefit." (PMID 35004676, 2021). "We assessed the similarity of immune-related gene expression profiles between the TCGA-PDAC cohort and a cohort of 32 melanoma patients receiving sequential CTLA-4 and PD-1 inhibitors." (PMID 34335594, 2021). "Several cases of opportunistic infections among patients with melanoma receiving the CTLA-4 inhibitor ipilimumab have been published, including invasive aspergillosis, cytomegalovirus-induced hepatitis, and pneumocystis pneumonia (PJP)." (PMID 34571876, 2021). "CTLA-4 protein was mainly expressed by melanoma cells and by a subset of tumor-infiltrating immune cells." (PMID 33196890, 2021). "By SubMap analysis, we further compared the expression data of Redox_scores from the TCGA and GEO cohorts, with another available dataset of 47 melanoma patients receiving PD-1 or CTLA-4 immunotherapy." (PMID 34804366, 2021). "In melanoma, PD-1 and CTLA-4 inhibitory antibodies (nivolumab, pembrolizumab, and ipilimumab) have been approved as single agents or in combination for treatment of patients with unresectable stage III and distant metastatic disease." (PMID 34360781, 2021). "Prior treatment with an anti-CTLA-4 was also shown to impact on the predictive ability of TCR repertoire dynamics in a cohort of melanoma patients treated with an anti-PD-1." (PMID 33602280, 2021). "Melanoma cells express CTLA-4, and the engagement of CTLA-4 on primary melanoma cell lines induced ADCC and TNFα production by NK cells." (PMID 33810032, 2021). "Anti-CTLA4 therapy using ipilimumab, has shown effective to improve overall survival in patients with melanoma and hepatocellular carcinoma, but is often used in combination with PD-1 inhibitors." (PMID 34568077, 2021). "Neutralizing tumor acidity with oral bicarbonate treatment synergized with either adoptive T cell transfer, anti-CTLA4 or anti-PD-1 treatment in two melanoma xenograft models." (PMID 33466735, 2021). "Transplantation of microbiota from melanoma patients to mice proved that B. fragilis favored the CTLA-4 blockade." (PMID 34917131, 2021). "used CT radiomics to identify five PsP cases from 50 melanoma patients treated with anti-cytotoxic T-lymphocyte antigen-4 (CTLA-4) inhibitor." (PMID 34733781, 2021). "In this study, the clinical benefits (OS) of anti-CTLA-4 and anti-PD-1 therapies in patients with MAP2K1/2-mutated melanoma were compared in a pooled cohort comprising a combination of six cohorts." (PMID 35069558, 2021). "A high expression of C5orf58 in patients with melanoma in different datasets indicated worse response to anti-PD-1/anti-CTLA-4 combined therapy, leading to worse overall survival or progression-free survival." (PMID 34178688, 2021). "A set of microRNAs contained in melanoma-derived EVs is found to be responsible for the conversion of monocytes into MDSCs and their baseline levels in plasma clustered with the clinical efficacy of CTLA-4 or PD-1 blockade in melanoma patients." (PMID 35003065, 2021). "Treatment with immune checkpoint inhibitors (ICIs), including antibodies targeting cytotoxic T lymphocyte antigen-4 (CTLA-4) and programmed cell death-1/programmed cell death ligand 1 (PD-1/PD-L1), is becoming a novel therapeutic paradigm for melanomas." (PMID 35069558, 2021). "Increased B cell density in the TME facilitates the establishment of TLSs and promotes responsiveness to PD-1/CTLA4 immunotherapy in melanoma." (PMID 34568077, 2021). "Treatment with CTLA-4 blockage has shown immense promise in melanoma patients yet only a portion of patients respond and over 80% of patients experience some level of adverse effect." (PMID 33391977, 2021). "Sade-Feldman and colleagues analyzed escape lesions from five melanoma patients treated with Ipilimumab (anti-CTLA4 Abs) and found LOH in B2M in 29.4% of the cases." (PMID 34680201, 2021).
melanoma (continued). "The novel anti-CTLA4 agents have already been approved or are under examination in the context of treatment of melanoma, non-small cell lung cancer, oesophageal squamous cell carcinoma and renal cell carcinoma." (PMID 33802937, 2021). "After nearly a century of research, immunotherapy was established as an anticancer frontline treatment when the immune checkpoint inhibitor (ICI) ipilimumab (anti-CTLA-4) was approved in 2011 for melanoma treatment." (PMID 34572799, 2021). "Our results showed that the CXCL13, FCRLA, MS4A1, and PLA2G2D were positively correlated with the level of CTL infiltration in the melanoma patients treated with anti-PD-L1 or anti-CTLA4." (PMID 34395521, 2021). "The first such agent, ipilimumab, was a monoclonal antibody against cytotoxic T-lymphocyte-associated protein 4 (CTLA4) and was approved in March 2011 to treat patients with late-stage melanoma." (PMID 34064074, 2021). "Anti-PD1 and anti-CTLA4 treatments are effective in melanoma immune therapy and, intriguingly, their effectiveness is marked by increased expression of ICOS." (PMID 35052731, 2021). "ICIs have revolutionized the therapeutic scenario of melanoma patients, the current standard treatment in advanced stages being antibodies against programmed death-1 (PD-1) (i.e., pembrolizumab, nivolumab) and CTLA-4 (i.e., ipilimumab)." (PMID 34440824, 2021). "The melanoma patients showed a higher objective response rate to anti-PD-1 therapy (42.2%) and the anti-PD-1 and anti-CTLA-4 combination therapy (65.6%)." (PMID 33915876, 2021). "Similar results were described recently by another group using the TA99 mAb with the anti-CTLA-4 mAb or the agonist anti-CD137 mAb in the B16F10 mouse melanoma model." (PMID 34572847, 2021). "Although various molecules/antigens have been proposed as possible immunotherapy targets, only anti-CTLA4 antibody and anti-PD-1/L1 antibody are available for immunotherapy against melanoma in clinical practice." (PMID 35069558, 2021). "High numbers of MDSCs in the peripheral blood were associated with poor overall survival in a phase I/II study of melanoma patients treated with anti-PD1 therapy after progressing on anti-CTLA4 therapy." (PMID 34944914, 2021). "In a murine model of melanoma, CSF-1R blockade successfully depleted MDSCs and also re-sensitized the tumors to therapies targeting CTLA-4, PD-1, and IDO." (PMID 34944914, 2021). "The use of monoclonal antibodies targeting CTLA-4, PD-1 and PD-L1 has seen excellent success, especially in settings such as melanoma and non-small-cell lung cancer." (PMID 33995362, 2021). "It has already been shown that subset of melanoma patients showing deletion of IFN gene cluster is resistant to anti-CTLA4 immunotherapy proposing that deletion of IFN gene cluster can be used a prognostic biomarker for immunotherapy resistance." (PMID 34555656, 2021). "In a melanoma mouse model resistant to a combination of anti-PD-L1 and anti-CTLA-4 treatment, PMN-MDSCs induced T-cell apoptosis by expressing FasL." (PMID 34203451, 2021). "When tumor-delivered exosomes are in touch with immune cells, they carry IL-10 and TGF-β that enhance Treg expansion and increase expression of CTLA-4 on Tregs to promote immune suppression in melanoma." (PMID 34806028, 2021). "Radiotherapy can facilitate the immune recognition of immunologically “cold” tumors and enhance the efficacy of anti-PD-1 and anti-CTLA-4 immune checkpoint inhibitors (ICIs) in melanoma." (PMID 34359580, 2021). "In 2014, TMB as a biomarker predictor was found for the first time to predict the efficacy of CTLA‐4 immunotherapy in patients with advanced melanoma." (PMID 34033229, 2021). "Regulatory T cells are known to be involved in anti-tumor immunity in melanoma patients, and the importance of therapeutic application of CTLA4 is proven in melanoma." (PMID 33669410, 2021).
melanoma (continued). "Ipilimumab was the first FDA-approved recombinant humanized anti-CTLA-4 immunoglobulin G1 monoclonal antibody in 2011 for the treatment of advanced melanoma in patients who cannot be surgically cured or have metastasis." (PMID 34917131, 2021). "Clinically, ICI resistance has been well characterized to correlate with the presence of TAMCs, as increased circulating levels of MDSCs have been shown to correspond with poor response to anti-CTLA-4 therapy in melanoma patients." (PMID 34512641, 2021). "Pretreatment genomic profiles and clinical characteristics of 631 melanoma patients treated with ICIs (i.e., inhibitors of CTLA-4, PD-1/PD-L1, or both) were comprehensively curated." (PMID 34795662, 2021). "Available retrospective case series assessing anti-CTLA-4 treatment with pre-existing autoimmune disease has emerged in the melanoma literature with a trend toward increased occurrence and severity of irAE when compared with historical controls." (PMID 34660286, 2021). "Ipilimumab, a monoclonal anti-CTLA4 antibody, paved the path for promising treatments, particularly in advanced forms of numerous cancers like melanoma." (PMID 33767992, 2021). "It has been shown that sequentially treatment with Tα1 and anti-CTLA4 significantly increased overall survival of melanoma patients." (PMID 34899700, 2021). "The pioneering checkpoint inhibitor ipilimumab, which is a mAb that targets CTLA4, was approved for advanced melanoma in 2011." (PMID 34064074, 2021). "The FNC‐fabricated nanovaccines when combined with anti‐CTLA‐4 show potency in lymph node targeting, DC antigen presentation, and T cell immune activation, leading to prophylactic and therapeutic efficacy in a melanoma mouse model." (PMID 34386315, 2021). "Case reports of transverse myelitis in patients with melanoma who received anti-CTLA-4 or combination anti-CTLA-4 and anti-PD-1 have been described." (PMID 34201529, 2021). "For example, in the context of melanoma, antibody blockade of CTLA-4 results in both a strong increase in both CD8+ and CD4+ T cell infiltration and a reduced proportion of intratumoural Tregs in vivo." (PMID 33953725, 2021). "CTLA-4 and PD-1 inhibitors are immune checkpoint inhibitors showing acceptable results in lung cancer and melanoma." (PMID 34540918, 2021). "Since ctLA-4 inhibitors were approved for melanoma in 2011, PD1/PD-L1 inhibitors have now been used to treat more than 20 different cancers, including colon cancer." (PMID 34912802, 2021). "In contrast to glioblastoma, combined anti-PD1 and anti-CTLA4 have intra- and extracranial activity in melanoma." (PMID 34859239, 2021). "Defects in the INF-gamma signaling pathway were similarly shown to confer resistance to anti-CTLA-4 therapy in melanoma patients." (PMID 33602280, 2021). "Several genomic features, such as high mutational load, high neoantigen load, and tumour clonality have been found to be predictive of a favourable response to anti-CTLA-4 therapy in melanoma patients." (PMID 35069558, 2021). "Anti-CTLA-4 mAb strongly reduces the proportion of Tregs in the TME from the murine melanoma tumor model (B16), whereas, in human tumors, the TA-Tregs proportion does not seem significantly impacted." (PMID 33924428, 2021). "Univariate analyses showed that a female sex, melanoma, and the use of anti-CTLA-4 inhibitor were significantly correlated with ≥ grade 3 AST or ALT elevations." (PMID 34046801, 2021). "For both of these tumor studies, melanoma and hepatocellular carcinoma, the combination of CTLA-4 and histotripsy yielded significantly reduced tumor volume compared to either treatment individually." (PMID 34136405, 2021). "Another study found a decrease in Bacteroidales and Burkholderiales abundances and an increase in Clostridiales in patients with melanoma receiving anti-CTLA4 therapies." (PMID 34361904, 2021).
melanoma (continued). "NK cell was relatively more effective for predicting response to anti-PD-1 therapy, while B lineage obtained relatively better performance for melanoma patients under anti-CTLA-4 therapy." (PMID 33915876, 2021). "IPS has been confirmed to have a predictive value in melanoma patients treated with the CTLA-4 and PD-1 blockers." (PMID 34722522, 2021). "For CTLA4, Buchbinder and Desai propose in the article that CTLA4 is a negative regulator of T cell immune function and participates in all aspects of immunotherapy for melanoma, non-small-cell lung cancer, and other cancers." (PMID 34671419, 2021). "In another study, 65 cytokines were profiled in patients with unresectable stage III or IV melanoma treated with anti-PD-1 monotherapy (cohort 1) or anti-PD-1 plus anti-CTLA-4 (cohort 2)." (PMID 34367136, 2021). "Prior systemic treatment had been administered in 2/20 melanoma patients (anti-CTLA-4 and BRAF-targeted therapy)." (PMID 34071888, 2021). "Then, we applied 11C-l-1MTrp to longitudinally monitor whole-body IDO1 variations in immunocompetent melanoma-bearing mice treated with l-1MTrp plus either chemotherapeutic drugs or antibodies targeting PD-1 and CTLA4." (PMID 34148865, 2021). "To date, in-depth characterization of two of the immune checkpoint proteins and their regulatory effects yielded a design of drugs which were approved for treatment of advanced melanoma, CTLA-4 and PD-1 inhibitory proteins and PD-L1, a ligand of PD-1." (PMID 34356899, 2021). "The combination of PD-1 and CTLA-4 inhibitors (e.g., nivolumab and ipilimumab) has shown a synergistic effect and efficacy in melanoma and other cancers." (PMID 33477635, 2021). "The anti-CTLA-4 antibody ipilimumab has shown durable anti-tumor activity and prolonged survival in patients with advanced melanoma, but is prone to immune-related adverse events (IAEs)." (PMID 34539412, 2021). "All four cases received anti-CTLA-4 treatment for melanoma, and one of them was treated with a combination of anti-CTLA-4 and anti-PD1 regimens." (PMID 34359715, 2021). "Current evidence showed that inhibitors for immune checkpoint molecules such as CTLA-4, PD-1, and PD-L1 are beneficial in the management of various malignancies, such as lung cancer, malignant melanoma, and renal cell cancer." (PMID 35008367, 2021). "Recent reports suggest DNA methylation of genes encoding for the immune checkpoints 4-1BB, LAG-3, PD-L2, and CTLA-4 as predictive biomarkers for response to ICB in melanoma." (PMID 33196890, 2021). "Based on our observations of the potential value of NLRC5 as a biomarker in the anti-CTLA4 treatment cohort, we were inspired to extend the analysis to melanoma patient cohorts treated with anti-PD1 therapy." (PMID 33547395, 2021). "The increased density of CTLA-4 on the melanoma cells is due to the activation of the JAK1/2 pathway, mediated by interferon-gamma (IFN-γ)." (PMID 33692796, 2021). "A recent study found that NKG7 and GNLY were overexpressed in patients that responded to anti-PD-1 and CTLA-4 in malignant melanoma." (PMID 33804039, 2021). "In a previous study, we demonstrated that selective blockade of sCTLA-4 was as effective as pan-CTLA-4 blockade at reducing lung tumor frequency in the B16F10 model of melanoma lung metastasis." (PMID 35069536, 2021). "Immunotherapy with several checkpoint blockers targeting programmed cell death protein 1 (PD-1), PD-1 ligand (PD-L1), or cytotoxic T lymphocyte antigen-4 (CTLA-4) has resulted in significant improvement in clinical outcomes of melanoma patients." (PMID 34040608, 2021). "In a preclinical study of murine melanoma, the combination of a DNA-based vaccine with dual CTLA-4 and PD-1 blockade increased the intratumoral infiltration of CD8+ T cells." (PMID 33801815, 2021). "Meanwhile, a synergy of INCB23843, an analogue of epacadostat, with anti-PD-L1 or anti-CTLA-4 antibodies, respectively, was investigated in B16 melanoma models." (PMID 33557876, 2021).
melanoma (continued). "Mice inoculated with either parental YUMM1.7 or mutagenized YUMM1.7-CM melanoma cells according to our standard protocol, were randomly assigned to receive IP, isogenic or anti-CTLA-4/anti-PD-1 sera 3×/week (n = 6–10)." (PMID 34295826, 2021). "Several drugs are approved for malignant melanoma, including nivolumab (an antibody against PD-1), the proto-oncogene B-Raf inhibitor vemurafenib, ipilimumab (which targets CTLA-4), and the mitogen-activated extracellular kinase inhibitor trametinib." (PMID 34928463, 2021). "In 2010, it was shown that the hetero-combination of anti-CTLA-4/-PD-1 blocking antibodies displays an increased anti-tumor efficacy in mouse models of colorectal cancer and melanoma." (PMID 34572847, 2021). "The benefits of combined immune checkpoint blockade (CICB) therapy targeting CTLA-4 and PD-1, for the treatment of melanoma has proved highly effective in a subset of patients." (PMID 34658896, 2021). "Anti-Program Death (PD) Pathway and anti-CTLA-4 mAbs—the PD pathway refers to one of the check points which drive melanoma progression." (PMID 35011682, 2021). "BRAFV600 melanoma patients are also eligible to receive immunotherapy, specifically checkpoint inhibitors against PD-1 and CTLA-4." (PMID 34025662, 2021). "In this context, one publication showed that anti-CTLA-4 and anti-PD-L1 treatments were less efficient in reducing the growth of B16 melanoma cells in 19–26-month-old male and female mice." (PMID 34206425, 2021). "The blockade of immune checkpoints such as PD-1, PD-L1, and CTLA-4 has shown impressive results in a series of solid cancers (especially melanoma and non-small cell lung cancer)." (PMID 34276701, 2021). "Preclinically, we showed that Sunitinib had synergistic effect with CTLA‐4 mAb in the treatment of melanoma and NSCLC immune competent mice." (PMID 33510997, 2021). "In this study, the mice with B16 melanoma were resistant to CTLA-4 treatment but when the CTLA-4 treatment was combined with IDO inhibitor 1- methyltryptophan (1MT) the tumors showed sensitivity to anti-CTLA-4." (PMID 34829916, 2021). "In melanomas, we found CTLA-4 protein expressed predominantly on tumor cells and only on a small subset of infiltrating immune cells." (PMID 33196890, 2021). "All 84 single agent anti-CTLA-4 were prescribed for melanoma patients, with an ipilimumab dose of 3 mg/kg." (PMID 34068892, 2021). "In anti-CTLA4-treated patients of melanoma, several studies showed that a reduction in the frequency of naive-phenotype CD4+ or CD8+ T cells were associated with better OS in the blood." (PMID 34446007, 2021). "The combination of anti-PD-1 and anti-CTLA-4 agents was approved in 2015 for melanoma; overall survival at 5 years was 52% for ipilimumab/nivolumab vs. 44% for nivolumab alone." (PMID 34298632, 2021). "Ipilimumab, approved in the treatment of advanced melanoma, and tremelimumab, under development in several solid tumors, works by binding to CTLA-4 and blocking its immunosuppressive signal." (PMID 34440249, 2021). "Somatic mutations in SERPINB3, a gene encoding a protein of the serpin family of serine protease inhibitors, were reported to predict improved survival from treatment with anti-CTLA4 therapy in two independent cohorts of patients with melanoma." (PMID 34898561, 2021). "Despite the striking impact of anti-PD-1 and anti-CTLA-4 drugs on the survival rates of melanoma patients, several problems arise from these treatments." (PMID 33435389, 2021). "Using SubMap analysis, we mapped the expression profiles of three immune subtypes (C1, C2, and C3) with another published cohort involving 47 melanoma patients who were treated with a PD-1 or CTLA-4 immune checkpoint inhibitor." (PMID 34621742, 2021). "In mice and patients with melanoma following anti-CTLA-4 therapy, T cell responses specific for Bacteroides thetaiotaomicron or Bacteroides fragilis were associated with the efficacy of CTLA-4 blockade." (PMID 34361904, 2021).